AFM (afamin)
Description:
Functions as a carrier for hydrophobic molecules in body fluids (Probable). Essential for the solubility and activity of lipidated Wnt family members, including WNT1, WNT2B, WNT3, WNT3A, WNT5A, WNT7A, WNT7B, WNT8, WNT9A, WNT9B, WNT10A and WNT10B. Binds vitamin E. May transport vitamin E in body fluids under conditions where the lipoprotein system is not sufficient. May be involved in the transport of vitamin E across the blood-brain barrier.
Synonyms: ALB2; ALBA; ALF
Tractability: Small molecule: a structure with a bound ligand is known. Antibody: UniProt places it where antibodies can reach, with high confidence; its Gene Ontology location is reachable by antibodies, with high confidence; UniProt predicts a signal peptide or a membrane-spanning region. PROTAC: its protein half-life has been measured.
Gene: Protein-coding gene on chromosome 4 (73,481,665 to 73,504,036, forward strand). Ensembl gene ENSG00000079557.
Subcellular location: Secreted
Subcellular location (Human Protein Atlas): Plasma membrane; Predicted to be secreted
Gene Ontology:
Molecular function: protein binding; vitamin E binding
Biological process: protein stabilization; protein transport within extracellular region; vitamin transport; response to nutrient levels
Cellular component: blood microparticle; extracellular exosome; extracellular region
Genetic constraint (gnomAD): Loss-of-function variants: 64 observed, 54.73 expected, observed/expected ratio (o/e) 1.17, 90% interval 0.95 to 1.44. The upper end of that interval is the gene's LOEUF score, 1.44, which puts it in group 5 of 6, group 1 being the genes least tolerant of losing a copy. Missense variants: 634 observed, 605.62 expected, observed/expected ratio (o/e) 1.05, 90% interval 0.98 to 1.12. Synonymous variants: 208 observed, 204.64 expected, observed/expected ratio (o/e) 1.02, 90% interval 0.91 to 1.14.
Homologues: Orthologues: chimpanzee AFM (99% identical), macaque AFM (93% identical), rabbit AFM (75% identical), dog AFM (75% identical), pig AFM (74% identical), guinea pig AFM (74% identical), rat Afm (68% identical), mouse Afm (68% identical), tropical clawed frog alb (28% identical). Paralogues in human: AFP (39% identical), ALB (35% identical), GC (17% identical).
Diseases named in the same sentence as AFM in open-access papers:
AFM is named in the same sentence as 70 diseases in open-access papers, as found by Europe PMC text mining. Sharing a sentence is not in itself a finding about the gene and the disease. The quoted sentences say what the papers report.
metabolic syndrome (23 papers, 2014 to 2026). A cluster of metabolic risk factors for CARDIOVASCULAR DISEASES and TYPE 2 DIABETES MELLITUS. "Large epidemiological studies are needed to fully elucidate the role of afamin in pathologies associated with metabolic syndrome such as obesity, diabetes mellitus, and hepatic steatosis." (PMID 36769494, 2023). "Adropin and afamin, the newly discovered peptides, correlate with inflammation and its associated conditions, such as hyperlipidemia and metabolic syndrome." (PMID 37835901, 2023). "In the study, increased afamin levels were linked with metabolic syndrome markers such as high blood glucose, dyslipidemia, obesity, high blood pressure, type 2 diabetes mellitus, and pre-eclampsia." (PMID 37835901, 2023). "Our aim was to evaluate the associations of serum afamin with glucose homeostasis, atherogenic dyslipidemia, and other adipokines in severe obesity to clarify the early metabolic alterations." (PMID 36835525, 2023). "These transgenic mice data yielded the same results as human population-based studies showing that afamin was strongly associated with the prevalence and development of metabolic syndrome." (PMID 36769494, 2023). "Afamin is a vitamin E-binding glycoprotein expressed mainly in the liver and is associated with many metabolic diseases, such as type 2 diabetes, metabolic syndrome, and obesity." (PMID 36204290, 2022). "Blood afamin levels are associated with many diseases, such as obesity, pregnancy pathologies, polycystic ovary syndrome, type 2 diabetes, hypertension, and dyslipidemia." (PMID 34945088, 2021). "Meta-analysis of large population studies clearly showed that plasma concentrations of afamin are strongly associated with prevalence and development of metabolic syndrome." (PMID 34603196, 2021). "Afamin plays a role in anti-apoptotic cellular processes related to oxidative stress and is associated with insulin resistance and other features of metabolic syndrome." (PMID 29587878, 2018). "Plasma levels of afamin, a vitamin-E binding glycoprotein, have been strongly associated with the development of metabolic syndrome in three independent human cohorts." (PMID 30594242, 2018). "Very recently, the human plasma vitamin E-binding protein afamin was reported to be highly significantly associated with criteria for metabolic syndrome in three independent human general populations." (PMID 25208973, 2014). "High plasma concentrations of the vitamin E-binding protein afamin have been previously shown to be associated with insulin resistance and metabolic syndrome." (PMID 25208973, 2014). "Furthermore, increased afamin levels have been linked with the development of the metabolic syndrome such as high blood glucose, dyslipidemia, obesity, and type 2 diabetes mellitus." (PMID 37835901, 2023). "A study showed that afamin values increased in correlation with the increase in body mass index of patients with gestational diabetes mellitus, whereas another study indicated that serum afamin values were associated with all metabolic syndrome components." (PMID 36769494, 2023). "Further, epidemiological studies on more than 5,000 subjects demonstrated that plasma afamin is a predictor for the prevalence and the incidence of metabolic syndrome." (PMID 38245742, 2024). "Today, the role of afamin in the pathogenesis of metabolic syndrome and obesity development as well as its relationship with appetite hormones are being investigated in human and animal models." (PMID 36769494, 2023). "There are many studies showing that afamin is present at high levels by showing a positive correlation with the components of obesity and metabolic syndrome." (PMID 36769494, 2023). "Our findings are fully in agreement with previous results indicating that afamin is an excellent early marker of metabolic syndrome and other related pathologies such as hypertension." (PMID 36014793, 2022).
metabolic syndrome (continued). "A study conducted in mice revealed a strong correlation between the increased afamin levels and development of metabolic syndrome and its components, i.e., hyperlipidemia, hyperglycemia, and increased body weight." (PMID 35457182, 2022). "Based on large epidemiological studies (Bruneck, SAPHIR, KORA F4), afamin has been proposed as a clinically relevant early marker of metabolic syndrome, T2D, gestational diabetes and pre-eclampsia." (PMID 34603196, 2021). "Transgenic mice overexpressing human afamin also show increased body weight, glucose, and lipid levels, further linking afamin to the metabolic syndrome." (PMID 32830851, 2020). "In that work, data from a prospective study design as well as corresponding data from afamin-transgenic mice suggest a role of afamin in the development of metabolic syndrome." (PMID 25208973, 2014). "The relationships between these proteins and SES have not previously been investigated, although afamin is associated with the development of metabolic syndrome, which varies with SES." (PMID 38951914, 2024). "However, several large human association studies and a small pilot study in transgenic mice suggested interrelations between circulating afamin and the development/progression of various components of metabolic syndrome and diabetes." (PMID 34603196, 2021). "Afamin is a liver-produced glycoprotein, a potential early marker of metabolic syndrome." (PMID 34603196, 2021). "Afamin, which is a human blood plasma glycoprotein, a putative multifunctional transporter of hydrophobic molecules and a marker for metabolic syndrome, poses multiple challenges for crystallographic structure determination, both practically and in analysis of the models." (PMID 31793901, 2019). "Thus, afamin can serve as a prognostic factor for the future development of metabolic syndrome in young individuals, especially women with insulin resistance." (PMID 31781629, 2019). "Moreover, serum concentrations of the liver-produced glycoprotein afamin correlate with hepatic fat contents and could therefore serve as an early marker of metabolic syndrome." (PMID 41487453, 2026). "Thus, our findings confirm that young women with PCOS are more likely to have metabolic syndrome, and afamin might serve as a discriminatory predictive parameter of IR in young PCOS patients." (PMID 25208973, 2014). "It has been observed that an increase in oxidative stress and the occurrence of related conditions (metabolic syndrome, T2DM, insulin resistance, obesity) correlate with elevating the serum afamin concentrations." (PMID 35457182, 2022). "LDL and total cholesterol, the height of which is considered as dyslipidemia, decreased statistically in both our study and the previous study, while the decrease in afamin was not significant in either study." (PMID 36769494, 2023). "Strong correlations were found between large and small HDL subfraction levels, oxLDL, mean LDL size, the components of metabolic syndrome and serum afamin concentrations in obese non-diabetics." (PMID 35053264, 2022). "The association between afamin and hepatic lipids was not explored, since the previous large epidemiological studies aimed at exploring afamin as an early marker of metabolic syndrome and T2D did not measure hepatic lipid content." (PMID 34603196, 2021). "Prompted by these observations, we measured afamin concentrations in patients with and without PCOS and investigated the association between afamin, IR and metabolic syndrome as a first step in establishing afamin as a marker for the development of metabolic syndrome in PCOS women." (PMID 25208973, 2014).
Insulin resistance (18 papers, 2014 to 2025). Increased resistance towards insulin, that is, diminished effectiveness of insulin in reducing blood glucose levels. "On the other hand, considering the strong association of afamin with WC, AST levels and measures of IR, higher afamin levels in long-term GH-deficiency are presumably associated with abdominal obesity, consequent insulin resistance and NAFLD." (PMID 38379862, 2024). "Increased serum afamin level was found to be associated with insulin resistance (IR), MS, and type 2 diabetes mellitus (T2DM)." (PMID 38379862, 2024). "Previous studies have also reported that elevated serum afamin levels are associated with insulin resistance and with increased glucose concentrations, which are involved in the development of NAFLD." (PMID 35800214, 2022). "Higher afamin levels are strongly associated with MS and insulin resistance (IR)." (PMID 38379862, 2024). "The development of insulin resistance in obese people and the inflammation process that begins with obesity may be the cause of elevated serum afamin." (PMID 36769494, 2023). "A pooled analysis in more than 20.000 individuals confirmed that afamin was strongly associated with insulin resistance and that it could be considered an independent strong predictor of type 2 diabetes (T2D)." (PMID 34603196, 2021). "Increased afamin concentrations were identified as an early biomarker for gestational diabetes and pre-eclampsia and have been positively associated with insulin resistance in patients with polycystic ovary syndrome." (PMID 34603196, 2021). "A large population-based cohort study found a robust link between afamin and insulin resistance, as well as the prevalence and incidence of type 2 diabetes." (PMID 38375199, 2024). "The role of afamin in the pathogeneses of both T2DM and GDM is suggested by its association with the occurrence of insulin resistance." (PMID 35457182, 2022). "Further studies are needed to clarify the role of afamin in obesity and the development of insulin resistance." (PMID 35053264, 2022). "Exercise-related changes in afamin were paralleled by reciprocal changes in insulinemia, insulin resistance and visceral adiposity." (PMID 34603196, 2021). "This is in line with the studies examining afamin in patients with polycystic ovary syndrome, where insulinemia and parameters of insulin resistance were identified as the best determinants of elevated circulating afamin." (PMID 34603196, 2021). "Recent studies showed that afamin can bind to thioredoxin, leading to oxidative stress and, consequently, to insulin resistance." (PMID 34803906, 2021). "The increasing knowledge of adropin, afamin, and neudesin and the regulation of glucose metabolism and insulin resistance allows for the assessment of the differences in their concentrations between the groups with varied duration of diabetes mellitus (DM)." (PMID 31781629, 2019). "Two markers novel to this current report, increases of leptin (satiety hormone) and afamin (related to albumin), likely also reflect metabolic disturbances by corticosteroids, possibly downstream of insulin resistance." (PMID 27530235, 2016). "This suggests that afamin may contribute to the development of insulin resistance at an early stage." (PMID 35053264, 2022). "This and a strong relationship of serum afamin with HOMA-IR and fasting glycemia allows us to speculate that afamin is strongly associated with hepatic insulin resistance." (PMID 34603196, 2021). "More importantly, training-induced improvements in insulin resistance (fasting insulinemia: r=0.457; p=0.033; n=22, HOMA-IR) and visceral adiposity were positively associated with training-induced changes in circulating afamin concentration." (PMID 34603196, 2021). "Importantly, hepatic lipid content was the strongest predictor of serum afamin in a model comprising age, BMI and parameters of obesity and insulin resistance." (PMID 34603196, 2021).
Insulin resistance (continued). "We speculate that increased serum afamin levels may contribute to oxidative stress, insulin resistance and inflammation, ultimately leading to the development of GDM." (PMID 34803906, 2021). "In patients with PCOS, afamin correlated significantly with homeostatic model assessment-insulin resistance (HOMA-IR), fasting glucose, BMI, FTI, and SHBG (P<0.001), but in a multivariate linear model, only HOMA-IR remained significantly associated with afamin (P=0.001)." (PMID 24928911, 2014). "This study aims to explore the serum levels of neuregulin 4 (NRG4), afamin (AFM), and serpin family B member 1 (SERPINB1) in gestational diabetes mellitus (GDM) patients and their relationship with insulin resistance." (PMID 36072413, 2022). "Comparing pre- and post-treatment with nano-curcumin values revealed a significant decrease in fasting plasma glucose (FPG) (p=0.017), insulin, homeostatic model assessment of insulin resistance (HOMA-IR) (p=0.006), and afamin (p=0.047)." (PMID 33907673, 2021). "We set out to determine whether the concentration of afamin in the serum of women with polycystic ovarian syndrome (PCOS) is elevated in relation to the presence and severity of insulin resistance (IR)." (PMID 25208973, 2014). "Based on our results, it is not clear whether increased afamin levels in obesity contribute to the development of insulin resistance or are simply unrelated consequences of obesity." (PMID 35053264, 2022). "However, it is not clear whether increased afamin level in obesity contribute to the development of insulin resistance or is simply an unrelated consequence of obesity." (PMID 36837889, 2023).
type 2 diabetes (12 papers, 2019 to 2025). "Elevated serum afamin levels in prediabetes and type 2 diabetes patients are closely associated with liver lipid accumulation and liver injury, suggesting afamin’s potential as a biomarker." (PMID 40625923, 2025). "Higher afamin levels are significantly associated with the markers of obesity and the obesity-linked disorders such as metabolic syndrome, type 2 diabetes, and gestational diabetes." (PMID 36837889, 2023). "In a clinical study of more than 20,000 people, it had been proved that human vitamin E-binding glycoprotein Afamin was positively associated with HOMA-IR in type 2 diabetes mellitus (β=0.110 [95%CI 0.089-0.132], P=1.37×10-23)." (PMID 36452319, 2022). "A recent study of more than 20,000 individuals has suggested afamin as a potential biomarker for the identification of individuals at high risk of type 2 diabetes." (PMID 36104811, 2022). "In a large multicenter population-based study, circulating afamin was associated independently with prevalent and incident type 2 diabetes (OR 1.30 [95% CI 1.23–1.38]; p < 0.001) indicating that afamin can be a promising novel biomarker to identify subjects with a high risk of type 2 diabetes." (PMID 36837889, 2023). "Again, another study found a correlation between type 2 diabetes and afamin values, and it was thought that afamin could be a new marker for the follow-up of individuals at risk of type 2 diabetes." (PMID 36769494, 2023). "Serum afamin levels were also significantly associated with type 2 diabetes mellitus." (PMID 35800214, 2022). "Most studies assessing the relationship of adropin, afamin, and neudesin with glucose metabolism provide data obtained from research conducted on animal models, adults with type 2 diabetes, and women with gestational diabetes." (PMID 31781629, 2019). "Based on the data obtained from animal studies, adults with type 2 diabetes, and women with gestational diabetes, it seems that adropin, afamin, and neudesin play a major role in the regulation of glucose metabolism and insulin sensitivity." (PMID 31781629, 2019). "Most papers assessing the relationship of adropin, afamin, and neudesin with glucose metabolism provide research data from animal models, adults with type 2 diabetes, and women with gestational diabetes." (PMID 31781629, 2019). "Prediabetes and type 2 diabetes, but not obesity, were associated with increased serum afamin (p<0.001)." (PMID 34603196, 2021). "Evidence evaluating a possible role of afamin as a marker of hepatic lipid accumulation and liver disease in a context of obesity and type 2 diabetes is not available." (PMID 34603196, 2021).